PON1 (paraoxonase 1)
Description:
Hydrolyzes the toxic metabolites of a variety of organophosphorus insecticides. Capable of hydrolyzing a broad spectrum of organophosphate substrates and lactones, and a number of aromatic carboxylic acid esters. Mediates an enzymatic protection of low density lipoproteins against oxidative modification and the consequent series of events leading to atheroma formation.
Synonyms: PON; ESA; MVCD5
Tractability: Small molecule: a high-quality ligand is known. Antibody: its Gene Ontology location is reachable by antibodies, with high confidence; UniProt places it where antibodies can reach, with medium confidence; UniProt predicts a signal peptide or a membrane-spanning region. PROTAC: its protein half-life has been measured; a small molecule that binds it is known.
Target class: Enzyme; Hydrolase
Safety:
Unwanted effects reported when the protein is acted on. In parentheses: how it was acted on, where the effect was seen, and who reports it.
cardiovascular secondary events (source: ClinPGx)
platelet inhibition and better response (source: ClinPGx)
stent thrombosis (source: ClinPGx)
target vessel revascularization (source: ClinPGx)
Gene: Protein-coding gene on chromosome 7 (95,297,173 to 95,324,710, reverse strand). Ensembl gene ENSG00000005421.
Subcellular location: Secreted, extracellular space
Pathways (Reactome):
Drug ADME: Atorvastatin ADME
Metabolism: Synthesis of 5-eicosatetraenoic acids
Gene Ontology:
Molecular function: acyl-L-homoserine-lactone lactonohydrolase activity; aryldialkylphosphatase activity; arylesterase activity; calcium ion binding; phospholipid binding; protein homodimerization activity
Biological process: carboxylic acid catabolic process; lactone catabolic process; negative regulation of plasma lipoprotein oxidation; organophosphate catabolic process; phosphatidylcholine metabolic process; positive regulation of cholesterol efflux; response to toxic substance
Cellular component: blood microparticle; extracellular exosome; extracellular region; high-density lipoprotein particle; spherical high-density lipoprotein particle; endoplasmic reticulum membrane
Genetic constraint (gnomAD): Loss-of-function variants: 37 observed, 42 expected, observed/expected ratio (o/e) 0.88, 90% interval 0.68 to 1.16. The upper end of that interval is the gene's LOEUF score, 1.16, which puts it in group 5 of 6, group 1 being the genes least tolerant of losing a copy. Missense variants: 390 observed, 428.37 expected, observed/expected ratio (o/e) 0.91, 90% interval 0.84 to 0.99. Synonymous variants: 147 observed, 158.86 expected, observed/expected ratio (o/e) 0.93, 90% interval 0.81 to 1.06.
Homologues: Orthologues: chimpanzee PON1 (99% identical), macaque PON1 (96% identical), dog PON1 (88% identical), rabbit PON1 (86% identical), pig PON1 (85% identical), mouse Pon1 (82% identical), guinea pig PON1 (80% identical), rat Pon1 (77% identical), tropical clawed frog pon2 (56% identical), zebrafish pon2 (52% identical), zebrafish pon3.2 (51% identical), zebrafish pon3.1 (50% identical), and 6 more. Paralogues in human: PON2 (66% identical), PON3 (60% identical).
Diseases named in the same sentence as PON1 in open-access papers:
PON1 is named in the same sentence as 374 diseases in open-access papers, as found by Europe PMC text mining. Sharing a sentence is not in itself a finding about the gene and the disease. The quoted sentences say what the papers report.
atherosclerosis (276 papers, 2006 to 2026). A disease characterized by the build-up of fatty material and calcium deposition in the arterial wall resulting in partial or complete occlusion of the arterial lumen. "PON1 activity aids in inhibiting formation of foam cells, thereby reducing the risk of atherosclerosis." (PMID 40313882, 2025). "Serum levels of PON1 have been reported to be reversely associated with systemic oxidative stress and atherosclerosis risk." (PMID 39787248, 2025). "Another explanation for the role of medium HDL in atherosclerosis is the protein paraoxonase 1 (PON1) that is associated with HDL." (PMID 41160327, 2025). "Pon1−/− mice were also more susceptible to organophosphates and other neurotoxic agents and to atherosclerosis." (PMID 39125665, 2024). "PON1 can hydrolyze oxidized fatty acids, triglyceride hydroperoxides, and cholesterylesters, which are implicated in atherosclerosis; therefore, this is one of the mechanisms that saves the LDL from oxidation." (PMID 38474211, 2024). "Studies on animals showed a difference between the overexpression of PON1 associated with a higher resistance to inflammation and lipid oxidation, whereas those with lower levels were more susceptible to atherosclerosis." (PMID 38474211, 2024). "Initial studies have shown that Pon1−/− mice are highly susceptible to the toxicity of organophosphate insecticides and to atherosclerosis induced by the metabolic stress of a high-fat diet, or by ApoE depletion." (PMID 39594433, 2024). "The high-density lipoprotein (HDL)-associated antioxidant enzyme paraoxonase-1 (PON1) plays a role in several human diseases, including diabetes mellitus and atherosclerosis." (PMID 39683642, 2024). "Mice with PON1 gene deletion develop atherosclerosis faster than control mice on a high-fat, high-cholesterol diet; overexpression of PON1 in transgenic mice decreases atherosclerosis risk." (PMID 38911352, 2024). "Serum activity of PON1 present on HDL is inversely associated with ASCVD incidence in humans and in animals PON1 ablation and overexpression lead to increased and decreased atherosclerosis." (PMID 38887979, 2024). "By breaking down these oxidized lipids, PON1 helps prevent the formation of foam cells, thereby mitigating the risk of atherosclerosis." (PMID 38474781, 2024). "Most importantly, it can hydrolyze homocysteine-thiolactone (homocysteine-thiolactonase activity), and this is claimed to be linked with the beneficial action of PON1 in the prevention of protein honocysteinylation, cell damage and atherosclerosis." (PMID 38982880, 2024). "Paraoxonase-1 is an enzyme primarily synthesised in the liver and has been shown to have a protective effect against atherosclerosis, which is the underlying cause of several cardiovascular diseases, including ASCVD." (PMID 39114750, 2024). "Gene ablation or over-expression of human PON1 in rodent models is associated with increased and decreased atherosclerosis susceptibility respectively." (PMID 36873390, 2023). "As apolipoprotein E (APOE) and paraoxonase 1 (PON1) were shown to suppress atherosclerosis, we investigated the associations of common functional PON1 and APOE polymorphisms with plasma lipid levels and the risk for late complications in T2D patients." (PMID 38084238, 2023). "Our previous work has linked suppressed PON1 activity to both subclinical atherosclerosis measured by carotid plaque, as well as risk of cardiovascular events in a large, ~ 2000 patient developmental program of the RA therapeutic, tofacitinib." (PMID 36138190, 2023). "Studies have demonstrated PON-1’s role in ischemic stroke, one of the top neurological disorders linked with atherosclerosis." (PMID 37108044, 2023). "As a result, PON1 has been linked to various metabolic disorders, including atherosclerosis, type 2 diabetes, non-alcoholic fatty liver disease, and obesity." (PMID 37189434, 2023).
atherosclerosis (continued). "Towards the end of that decade Mackness joined the lipoprotein group in Manchester and we began to study PON1 in diseases associated with accelerated atherosclerosis." (PMID 36873390, 2023). "Initial studies in mouse models have shown that deletion of Pon1 in mice causes increased sensitivity to the toxic effects of organophosphate insecticides and increased susceptibility to atherosclerosis induced by a high-fat diet or ApoE depletion." (PMID 37175471, 2023). "The lipid-modifying, antioxidant, and anti-inflammatory properties of PON1 have been implicated in the prevention of atherosclerosis and its complications." (PMID 35628426, 2022). "In contrast, PON1 deficiency was frequently observed in lesions of atherosclerosis, which resulted in vascular OS and leukocyte adhesion." (PMID 35386842, 2022). "PON1 is one of the most investigated genes regarding predisposition to atherosclerosis based cardiovascular abnormalities." (PMID 36118876, 2022). "Its ability to inhibit lipid peroxidation, among other activities, resulted in numerous studies on the association of PON1 with atherosclerosis and cardiovascular disease." (PMID 35889799, 2022). "Further, PON-1-deficient mice demonstrate a higher risk for developing atherosclerosis compared to wild-type mice." (PMID 36140402, 2022). "First, reduced activity of PON-1 is linked with increased oxidant stress in atherosclerosis settings, a shared feature underlying the pathogenesis of CKD." (PMID 35624764, 2022). "We measured PON-1 because of its strong correlation with atherosclerosis and cardiovascular disease risk, with evidence showing its reduced activity in combustible cigarette smokers, and after subacute exposure to air pollution." (PMID 34298007, 2022). "Our results indicate a negative relationship between higher cholesterol consumption and PON1 activity, similarly to that found in mice susceptible to atherosclerosis." (PMID 33844899, 2021). "On the contrary, the occurrence of the T allele suppressed miR-616 binding, which resulted in PON1 gene overexpression and possible protection against atherosclerosis and stroke." (PMID 33670025, 2021). "They concluded that WPJ and WPOMxl delayed the development of atherosclerosis in diabetic patients through PON1 stabilization and increased the association of PON1 with HDL and its catalytic activity." (PMID 34796029, 2021). "PON1 activity was significantly higher in the group consuming turkey protein without sex differences, but its association with cross-sectional atherosclerosis was only observed in females." (PMID 34072167, 2021). "We found that proteins affected by the human PON1-Q192R polymorphism were significantly enriched in 11 canonical pathways, which are linked to atherosclerosis, thrombosis, and Alzheimer’s disease." (PMID 33260536, 2020). "Initially, we performed analyses wherein the association between each SNP and the Gensini score was examined individually, which showed only the PON1 c.575A>G polymorphism being independently associated with the extent of atherosclerosis." (PMID 32961879, 2020). "The PON1 L55M allele has been implicated in the aetiology of other health outcomes (i.e. atherosclerosis, cancer and leukaemia) besides those of neurobehaviour dysfunction." (PMID 32386510, 2020). "In humans, low PON1 activity is the independent risk factor of acute CV events and is associated with most traditional risk factors of atherosclerosis such as hypercholesterolemia, diabetes, and smoking." (PMID 32967340, 2020). "Our results suggest that the MPO c.−463AA and PON1 c.575GG genotypes increase the risk of more severe atherosclerosis." (PMID 32961879, 2020). "Altogether, these findings strongly associate the PON1 levels to atherosclerosis onset and development, showing the importance of a fully functioning enzyme to, ultimately, prevent plaque formation." (PMID 31430977, 2019).
atherosclerosis (continued). "Results of our study are in overall agreement with previously reported research regarding association of PON1 activity with atherosclerosis risk factors, although we show some valuable findings." (PMID 30935088, 2019). "Studies on animal models have demonstrated that overexpression of PON1 leads to an increased resistance to inflammation and atherosclerosis, whereas PON1 knockout mice are more susceptible to lipoprotein oxidation and increased inflammation." (PMID 31430977, 2019). "Consistently, a human study showed that MeHg exposure was associated with reduced activity of Paraoxonase 1 (PON1), an enzyme that inhibits systemic oxidative stress and guards against atherosclerosis and obesity." (PMID 31775748, 2019). "Our results show that the reduced concentration of PON1 in the blood of the test subjects is associated with the increased risk of atherosclerosis, because it plays a major role in this pathogenesis lipoprotein metabolic disorders." (PMID 31737129, 2019). "PON1 is expressed in advanced atherosclerotic intima, and PON1-deficient mice show an increased susceptibility to atherosclerosis." (PMID 31242230, 2019). "PON1-deficient mice are susceptible to the development of atherosclerosis, whereas it is inhibited by overexpression of human PON1 in mice." (PMID 30151068, 2018). "Low PON1 activity has been reported in previous studies as one of the leading factors causing atherosclerosis and myocardial infarction." (PMID 30044465, 2018). "Both the hypercholesterolemia and PON1 deficiency are independent risk factors for the development of atherosclerosis." (PMID 30044465, 2018). "A better understanding of factors upregulating PON1 status in humans will have a significant public health impact by saving patients who are otherwise susceptible to atherosclerosis due to their deficient PON1 status." (PMID 30044465, 2018). "When fed on a high-fat diet, PON1 (−/−) mice were more susceptible to atherosclerosis than PON1 (+/+) mice." (PMID 30545386, 2018). "Understanding a possibly protective role of PON1 activity in patients susceptible to atherosclerosis can help in taking early preventive measures for improvement of life span of hypercholesterolemia patients." (PMID 30044465, 2018). "PON1 transgenic mice had decreased oxidative stress and atherosclerotic lesions, whereas PON1 knockout mice had increased serum oxidative stress and were more susceptible to high-fat-diet-induced atherosclerosis." (PMID 29951533, 2018). "Studies suggest that high PON1 activity is associated with the reduction of atherosclerosis and low PON1 levels are considered an independent risk factor for coronary events and other metabolic diseases." (PMID 30360466, 2018). "Numerous clinical studies have shown an association of low PON1 activity with atherosclerosis and cardiovascular diseases." (PMID 30044465, 2018). "Our results highlight the importance of exploring PON1 as a therapeutic agent to accommodate the lower level of plasma PON1 in patients susceptible to atherosclerosis." (PMID 30044465, 2018). "Direct proof of its effects on atherosclerosis development was obtained from Pon1-deficient mice and their counterparts overexpressing human PON1 gene." (PMID 28212288, 2017). "The most convincing evidence for the PON1's association with atherosclerosis was discovered with transgenic mice." (PMID 27213056, 2016). "As such, PON1 plays a relevant role in determining susceptibility to atherosclerosis and cardiovascular disease." (PMID 27338244, 2016). "Evidence for the role of PON1 in the antioxidant property of HDL is provided by the findings that PON1 knockout mice are more susceptible to atherosclerosis when fed on a fat-rich diet." (PMID 27812605, 2016). "Reduced PON1 activities are assumed to increase the risk of atherosclerosis which is a stroke risk factor." (PMID 27774120, 2016).
atherosclerosis (continued). "We and others have demonstrated that lower plasma PON1 activity is associated with increased development and extent of atherosclerosis, and that high plasma PON1 activity has an antiatherosclerotic effect." (PMID 27869741, 2016). "Paraoxonase 1 (PON1) gene polymorphisms and polyphenols intake have been reported independently associated to lipid profile and susceptibility to atherosclerosis and cardiovascular disease." (PMID 27338244, 2016). "In line with this, PON-1 knockout mice show an enhanced susceptibility for developing atherosclerosis, whereas PON-1 overexpressing mice are protected from the development of atherosclerosis and exhibit reduced systemic measures of oxidation." (PMID 27304214, 2016). "PON-1 is an antioxidant enzyme which prevents atherosclerosis by associating with high-density lipoprotein (HDL)." (PMID 25785999, 2015). "In previous studies, we and others have demonstrated that lower plasma PON1 activity is associated with increased atherosclerosis." (PMID 26318157, 2015). "Genetic deletion of PON-1 in animal models of atherosclerosis is associated with increased oxidation of low-density lipoproteins (LDLs), increased macrophage oxidative stress, and increased atherosclerotic lesion size." (PMID 26697134, 2015). "The PON-1 activity has a protective role, while higher Hcy levels are considered an independent risk factor for atherosclerosis." (PMID 25586501, 2015). "It has been shown that PON-1 activity is associated with accelerated atherosclerosis but is also affected both by genetic polymorphism and by environmental factors including age, lifestyle, and pharmaceutical intervention." (PMID 26697134, 2015). "In fact, PON1-deficiency resulted in increased oxidative stress not only in serum, but also in macrophages, a phenomenon that can contribute to the accelerated atherosclerosis shown in Pon1-deficient mice." (PMID 26024295, 2015). "Paraoxonase 1 (PON1) has been implicated in the development of those conditions, especially atherosclerosis." (PMID 26024295, 2015). "Several studies have shown that PON1 knockout mice are susceptible to the atherosclerosis, whereas overexpression of PON1 in mice reduced atherosclerosis." (PMID 24465855, 2014). "Polymorphisms and abnormal enzymatic activity of PON1 have also been implicated in heart disease, osteoporosis, atherosclerosis, and cancer." (PMID 25322877, 2014). "There are evidences suggesting that PON1 is an HDL-associated antioxidant enzyme protecting against atherosclerosis by preventing from lipoprotein oxidation and hydrolyzing oxidized cholesterol and/or phospholipids in atherosclerotic lesions and oxidized LDL." (PMID 24644436, 2014). "PON2 and PON3 are also able to hydrolyze lactones similar to PON1, and they have also been implicated in the atherosclerosis process." (PMID 25405733, 2014). "It is well documented that PON1 deficiency is related to increased susceptibility for low-density lipoprotein oxidation and development of atherosclerosis." (PMID 24971380, 2014). "Decreased serum arylesterase activity, catalyzed by the high‐density lipoprotein–associated paraoxonase (PON)‐1, is associated with increased oxidant stress and atherosclerosis risk." (PMID 23557751, 2013). "In animal model studies, an accelerated development of atherosclerosis was shown in PON1 deficient mice." (PMID 24222847, 2013). "PON1-deficient mice are susceptible to the development of atherosclerosis, whereas overexpression of human PON1 in mice inhibits atherosclerosis development." (PMID 22690338, 2012). "Most studies focused on the anti-oxidant/anti-inflammatory properties of PON1 in association with the development of atherosclerosis and the role of the Q192R polymorphism as a genetic marker for CHD." (PMID 21569287, 2011). "Our data indicate that the low-antioxidant PON1 R192 allele is associated with increased pro-inflammatory cytokines known to be involved in the initiation process of atherosclerosis." (PMID 21569287, 2011).